MMP2 (matrix metallopeptidase 2)
Diseases named in the same sentence as MMP2 in open-access papers (continued):
Sharing a sentence is not in itself a finding about the gene and the disease.
lung carcinoma (continued). "We have investigated the association between the -735 C/T, the -1171 5A/6A, and the -1562 C/T polymorphisms in the MMP2, MMP3 and MMP9 genes, respectively, and the risk and survival of lung cancer." (PMID 22455335, 2012). "The expression of VEGFA and MMP-2 was lower in lung cancer resections compared to pneumothorax and the transplant biopsy." (PMID 22593690, 2012). "The main aim of this study was to investigate the relationship between 3 functional polymorphisms in the regulatory regions of the human gelatinases MMP2 and MMP9 and the human stromelysin MMP3 and lung cancer risk in the individuals from the CAPUA study." (PMID 22455335, 2012). "The enhancement of MMP-2 activity has been well characterized in highly metastatic human lung cancer cells." (PMID 23226337, 2012). "Immunohistochemical studies showed lower expression levels of VEGFA and MMP-2 in lung cancer resections compared to pneumothorax and transplant biopsies, while in contrast TIMP-1 and KDR expression was higher in lung cancer." (PMID 22593690, 2012). "Previous studies have demonstrated the extrinsic pathway of apoptosis was induced by extracellular Par-4 and siRNA mediated knock down of MMP-2 sensitized lung cancer cell apoptosis." (PMID 22962598, 2012). "We evaluated the effect of three polymorphisms in the promoter regions of two human gelatinases, MMP2 and MMP9, and the human stromelysin MMP3 on the risk and survival time of lung cancer." (PMID 22455335, 2012). "All groups had similar expression levels for most of the proteins analysed except TIMP-1 which was higher in the lung cancer resection, MMP-2 which was higher in lung transplant biopsy and VEGFA, which was elevated in pneumothorax samples." (PMID 22593690, 2012). "The present study demonstrated that fucoidan effectively down regulates the expression of MMP-2 through the inhibitions of PI3K-Akt-mTOR as well as ERK1/2 signaling pathways in A549 human lung cancer cells." (PMID 23226337, 2012). "Expression of antisense CD44 and treatment of cells with anti-CD44 blocked hyaluronic acid (HA)-dependent MMP-2 secretion and, subsequently, invasion of a human lung carcinoma cell line." (PMID 17343740, 2007). "To investigate whether S100A4-RAGE signaling influences hsa-miR-125b-5p and MMP-2 expression through JNK-MAPKs or ERK-MAPKs in A549 lung cancer cells, we employed specific MAPK inhibitors." (PMID 41155277, 2025). "TLR3/4 activation results in the upregulation of chemokines CCL2/MCP-1 and immunosuppressive factors VEGFA and MMP2, which collectively promotes lung cancer invasion and metastasis through the adaptor protein TICAM1/TRIF and the activation of downstream MAPK/NF-κB signaling pathway." (PMID 41293166, 2025). "FA could induce cell death of cell lung cancer cells (H1299) at a concentration of 0.06–0.6 μM by upregulating ROS, hydrogen peroxide, superoxide anion, and downregulating MMP2 and MMP9, colony formation, and AIG capacity." (PMID 40487371, 2025). "Here, we investigated whether NF-κB activation is involved in S100A4-RAGE-induced modulation of hsa-miR-125b-5p and MMP-2 in human A549 lung cancer (LC) cells." (PMID 41155277, 2025). "Among these, MMP-2 is of particular interest as an anticancer therapeutic target due to its high expression across multiple malignancies, including breast, cervical, bladder, gastric, and lung cancers." (PMID 41463322, 2025). "Together, these results consistently demonstrate that p38-MAPK and NF-κB signaling pathways play a key role in regulating miR-125b-5p expression and its downstream target MMP-2 in SHP-77 lung cancer cells, whereas ERK-MAPK and JNK-MAPK pathways appear to be non-contributory." (PMID 41155277, 2025). "This aligns with our findings, indicating that miRNA-targeted regulation of MMP-2 may be an effective strategy for mitigating lung cancer metastasis." (PMID 41155277, 2025).
lung carcinoma (continued). "Similarly, our study exhibit that silymarin have potential inhibition of MMP-2 and −9 in lung cancer A549 to hinder the Lung cancer migration." (PMID 39431222, 2024). "Additionally, thioredoxin reductase activity in A549 lung cancer cells and matrix metalloproteinase 2 (MMP-2) enzyme activity in colorectal carcinoma cells were both suppressed by myricetin." (PMID 39584904, 2024). "In conclusion, it can be proposed that AQP1 may promote the proliferation and migration of lung cancer cells in a manner dependent on MMP-2 and MMP-9120." (PMID 39440058, 2024). "Furthermore, miR-6884-5p mimics significantly inhibited EMT progression in lung cancer, as reflected by increased protein levels of MMP2 and E-cadherin, and a decreased protein level of N-cadherin." (PMID 38271114, 2024). "Similarly, earlier research has shown that berberine hinders lung cancer cell growth by affecting the matrix metalloproteinase 2 (MMP-2)/Bcl-2/Bax and Janus kinase 2 (Jak2)/vascular endothelial growth factor (VEGF)/NF-κB/AP-1 signaling pathways." (PMID 38334679, 2024). "Interestingly, non-coding RNAs found in TDSEVs can also influence ECM breakdown, for example, SEV lnc-MMP2-2 derived from lung cancer is able to modulate migration and invasion by raising MMP2 expression." (PMID 38243280, 2024). "Importantly, we observed that both the decrease in the MMP-2 concentration and the increase in the MMP-9 concentration further enhance the risk of lung cancer development." (PMID 37445754, 2023). "Specific genotypes affect MMP-2 and MMP-9 concentrations in both lung cancer patients and healthy controls, which may thereby increase lung cancer risk, disease aggressiveness, and patient survival outcomes." (PMID 37445754, 2023). "Within both of the CC and CT genotypes of the MMP-2-735C/T polymorphism, patients with all lung cancer subtypes (ADC, SqCC, and OLN) had statistically significant differences in their MMP-2 concentrations, with lower levels of MMP-2 observed compared to the non-smoking and smoking controls." (PMID 37445754, 2023). "Furthermore, RD24 showed matrix metallopeptidase 2 (MMP2) responsiveness, which improved lung cancer cell inhibition induced by the miRNA intracellularly." (PMID 37521428, 2023). "Curcumin has anti-metastatic potential by decreasing the invasiveness of cancer cells involved in the p-ERK and MEKK3 signaling pathways, leading to the inhibition of MMP-2 and MMP-9 and resulting in the inhibition of MMP-2 and -9 in human lung cancer A549 cells." (PMID 37888190, 2023). "In the previous decade, just five studies on the role of MMP-2 and MMP-9 polymorphism in lung cancer patients have been published and indexed in the MEDLINE (PubMed) database, which appears to be an understatement given the seriousness of the lung cancer problem." (PMID 37445754, 2023). "Prior to examining the impact of these specific MMP-2-735C/T and MMP-9-1562C/T genotypes on the MMP-2 and MMP-9 concentrations, we performed logistic regression analyses to estimate the impact of each examined factor on the risk of lung cancer." (PMID 37445754, 2023). "Next we investigated whether the MMP-2-735C/T and MMP-9-1562C/T genotypes were associated with environmental factors in lung cancer patients and healthy controls, as well as clinicopathological characteristics in lung cancer patients." (PMID 37445754, 2023). "However, the low pH conditions in the lysosomes and the abundant intracellular MMP‐2 synergistically destructed the nanoparticles and improved the release of miRNA, which was beneficial for lung cancer therapy." (PMID 37521428, 2023). "Drugs targeting MMP2 have been used for the treatment of cancer (marimastat), renovascular hypertension, and congestive heart failure (captopril), or investigated in clinical trials for the treatment of lung cancer (oleandrin)." (PMID 37726845, 2023).
lung carcinoma (continued). "Furthermore, to the best of our knowledge, this is the first study to show a possible relationship between the knockdown of POSTN expression in lung cancer cells in vitro and the downregulation of MMP-2." (PMID 35163164, 2022). "Strikingly, MICE and HIIE markedly reduced the expression of MMP9 and MMP2 in lung cancer tissues, respectively, which means that MICE may restrain the metastasis of lung cancer cells by decreasing the level of MMP9." (PMID 35371324, 2022). "Similarly, upregulated TRPM7 enhances the lung cancer stem cell-like phenotype and promotes lung cancer metastasis via the Hsp90α/uPA/MMP2 signaling pathway." (PMID 35887116, 2022). "Exosomes could also regulate the migration of lung cancer cells into the rich vasculature by promoting MMP-2 expression." (PMID 36230852, 2022). "In mechanism, C Chetty and his colleagues suggested that MMP-2 could up-regulate VEGF expression via integrin αvβ3/PI3K/AKT signaling in lung cancer cells." (PMID 35473511, 2022). "Our results showed that rhein plays a vital role in proliferation and metastasis of chemosensitive and chemoresistant lung cancer cells, and the mechanism may be related to the Stat3/Snail/MMP2/MMP9 pathway." (PMID 35178453, 2022). "One study proposed that MMP-2 may modify VEGF expression after observing reduced VEGF expression in A549 lung cancer xenograft tissue samples from mice treated with MMP-2 siRNA." (PMID 35565306, 2022). "Therefore, our results suggest that POSTN promotes the invasive ability of lung cancer cells, at least partly via tumor microenvironment factor MMP-2, highlighting MMP-2 as an effector of POSTN signaling in lung cancer cells." (PMID 35163164, 2022). "Therefore, the inhibition of the MMP-2 expression regulatory pathway is an important therapeutic strategy for preventing lung cancer metastasis." (PMID 35163164, 2022). "Silencing of POSTN could inhibit the migration and in vitro invasive potential of lung cancer cells, most probably via the downregulation of MMP-2 expression and activity as well as integrin-signaling related proteins." (PMID 35163164, 2022). "In summary, POSTN may regulate lung cancer cell invasiveness by modulating the expression of MMP-2 and may represent a potential target for novel therapeutic intervention for NSCLC." (PMID 35163164, 2022). "Exosomal miR-106b could enhance the invasive ability of lung cancer cells and increase MMP-2 and MMP-9 expression." (PMID 36230852, 2022). "Therefore, this study aims to analyze the effect of POSTN-silencing on migratory and invasiveness of lung carcinoma A549 cells and the expression of tumor microenvironment factor MMP-2 and integrin-signaling-pathway-related proteins." (PMID 35163164, 2022). "Similarly, MMP2 expression in lung cancer tissues was shown to be higher than that found in normal tissues and suggested to be related to the development of lung cancer." (PMID 34209215, 2021). "Likewise, the decrease in invasiveness was also observed when lung cancer cells were co-treated with curcumin (10 μM) and carboplatin (50 or 100 μM), through the repression of matrix metallopeptidase 2/9 (MMP-2/9) activities." (PMID 34299604, 2021). "Moreover, the data of upregulated MMP-2 expression also agreed with those reported in glioblastomas and lung cancer." (PMID 33817311, 2021). "In addition, damulin B was reported to inhibit the migration of human lung cancer A549 and H1299 cells by down-regulating the protein production of matrix metalloproteinase-2 and -9 (MMP-2 and -9)." (PMID 34684830, 2021). "Furthermore, the up-regulation of matrix metalloproteinase-2 (MMP-2) by HMGA1 promotes lung cancer transformation, and the blocking of MMP-2 expression inhibits cancer cell migration and invasion." (PMID 34072941, 2021).
lung carcinoma (continued). "Stimulation of TGF-β signaling could decrease the expression of NKG2DLs in lung cancer cells which might be related with increased expression of MMP2." (PMID 34253166, 2021). "Treatment of A549 and H1299 cells with the PI3K inhibitor, AKT inhibitor, or NFκB inhibitor led to decreased levels of both MMP2 and MMP9 in the media, suggesting the likely involvement of these proteins in the mechanism regulating the levels of MMP2/9 in the media of these lung cancer cells." (PMID 34209215, 2021). "We aimed to elucidate the regulatory mechanism of exosomal lnc-MMP2-2 in lung cancer brain pro-metastases and examine whether it could be a promising therapeutic target for patients with NSCLC." (PMID 34285192, 2021). "Correspondingly, fucoidan suppressed cancer cell migration and invasion in human lung cancer cells (A549 cells) via inhibition of MMP-2, wherein blocking of the ERK1/2 and PI3K-AKT-mTOR pathways was associated with the MMP-2-related anti-cancer effects of fucoidan." (PMID 33333858, 2020). "Naringenin inhibits proliferation and induces apoptosis of A549 cells by inducing death receptor 5 (DR5) expression in human lung cancer cells and Naringin also be able to inhibit Akt activity and down-regulates MMP-2 and MMP-9 to inhibit migration of A549 cells." (PMID 33265939, 2020). "Hence, further experiments involving the mutual regulation-mechanism of MMP2 in lung cancer cells should be done." (PMID 33115469, 2020). "Increased MMP2 correlates with malignant biological behavior of lung cancer and it could be a potential biomarker for diagnosis and prognosis of the disease." (PMID 33115469, 2020). "In addition, increase of MMP2 in lung cancer tissues was correlated with shorter survival of patients." (PMID 33115469, 2020). "In conclusion, results of the present study provide experimental evidence that myricetin can inhibit invasion and migration of radioresistant lung cancer cells (A549‐IR) by suppressing the expression of MMP‐2 and MMP‐9 through inhibition of the FAK‐ERK signaling pathway." (PMID 32328272, 2020). "A previous study suggested that EGCG could inhibit the invasion of CL1-5 lung cancer cells by suppressing MMP-2 expression through c-Jun N-terminal kinase signaling." (PMID 32198390, 2020). "Of these proteases, the expression of MMP-2 and MMP-9 are associated with lung cancer progression." (PMID 32349289, 2020). "In our study we did not detect significant association of rs243865 in MMP-2 with lung and colon cancer risk, however we observed higher frequency of TT genotype in lung cancer patients comparing to controls (5% vs. 3%)." (PMID 32765800, 2020). "However, poorly differentiated lung cancer showed a highly expressed MMP2 (10/19, 52.6%) compared with well differentiated lung cancer (2/14, 14.3%) (p = 0.022)." (PMID 33115469, 2020). "Kaempferol can inhibit Matrix metalloproteinase (MMP)-2 activity of human A549 lung cancer cells." (PMID 33265939, 2020). "Nano-EGCG may inhibit lung cancer cell invasion through matrix metalloproteinase (MMP)-2- and MMP-9-independent mechanisms." (PMID 32198390, 2020). "In our study, these two factors were implicated into the regression equation and the regression equation was as H(t) = [h0(t)] e (2.01X8 + 1.49X9), which suggested that determining the expression of MMP2 in lung cancer tissues is helpful for predicting the prognosis of lung cancer patients." (PMID 33115469, 2020). "In addition, suppression of lung cancer invasion is perceived in HDAC inhibitor‐repressed MMP‐2/9 activity (Karthik, Sankar, Varunkumar, & Ravikumar, 2014; Liu, Chang, Chiang, & Hung, 2003)." (PMID 32180962, 2020). "Of those identified target genes, we selected HSPA6, histidine‐rich glycoprotein (HRG), ubiquitin D, prostaglandin E synthase (PTGES), tyrosine kinase (TXK), and MMP2 and measured those gene expressions in eight lung cancer cells 48 h after treatment with acRoots at 10 mg/mL." (PMID 32508044, 2020).
lung carcinoma (continued). "As an overexpression of the lncRNA, MVIH is associated with tumor angiogenesis and MVIH expression is upregulated in lung cancer, further influencing MMP2 and MMP9, it may affect lung cancer tumor angiogenesis." (PMID 32992718, 2020). "Results of 2 meta-analyzes indicate that rs243865 in MMP-2 correlates with lung cancer risk in Asian populations, but not Caucasians." (PMID 32765800, 2020). "Furthermore, IL-6 inhibition dramatically suppressed MMP2/9 and vimentin expression but elevated E-cadherin expression all four lung cancer cell lines treated with aADSCs-CM." (PMID 31196220, 2019). "ERK3 stimulates lung cancer cell invasiveness both in vitro and in vivo by phosphorylating the steroid receptor coactivator 3 oncoprotein, which causes an upregulation of different MMP genes including MMP2." (PMID 31311187, 2019). "Likewise, CoQ10 caused a decrease in O2− level in mitochondria, inhibited MMP2 and MMP9 activity, and reduced tumor volume and the number of metastasis in mouse lung carcinoma." (PMID 30984333, 2019). "Among these, MMP-9 and MMP-2 play a critical role in the progression of lung cancer." (PMID 29565268, 2018). "Furthermore, we showed for the first time that TRPM7 regulates the CSCs activities of lung cancer cells by modulating the Hsp90α/uPA/MMP2 signaling pathway." (PMID 30477473, 2018). "MMP-2 and -9; gelatinases, are very closely associated with the metastatic properties of lung cancer, which suggests that creating potent MMP-2 and MMP-9 inhibitors should be an important goal in lung cancer therapy." (PMID 29679218, 2018). "Furthermore, we found that lnc‐MMP2‐2 levels were positively correlated with MMP2 levels during lung cancer progression." (PMID 30256540, 2018). "Moreover, exosomal lnc‐MMP2‐2 promoted MMP2 expression in TGF‐β‐mediated lung cancer invasion and increased vascular permeability." (PMID 30256540, 2018). "Comparing lung cancer patients with benign group, the best cutoff level of MMP-2 in BALF for SCC, ADC, and SCLC were 1.794 ng/ml, 1.643 ng/ml, and 0.906 ng/ml, corresponding AUC was 0.7458 (95% CI, 0.6097–0.8820), 0.7708 (95% CI, 0.6513–0.8904), and 0.7396 (95% CI, 0.5937–0.8854), respectively." (PMID 29113325, 2017). "In this study, we found that curcumin stimulates the expression of miR-98, which in turn negatively regulates LIN28A-induced lung cancer invasion and migration may through inhibition MMP2 and MMP9." (PMID 28587210, 2017). "Moreover, PG has inhibited RhoA and MMP-2 protein expression in lung cancer 95-D cell line resulting in invasion inhibition." (PMID 28714874, 2017). "However, the expression of MMP-2 and its inhibitor the tissue inhibitors of matrix metalloproteinase 2 (TIMP-2) in airways of lung cancer and its diagnostic value is still unclear." (PMID 29113325, 2017). "Compared to HD, levels of VEGF and MMP-2 were insignificantly changed in lung cancer patients." (PMID 27811960, 2016). "Then, we demonstrated that basigin-2 could promote lung cancer cells invasion, metastasis and proliferation through upregulating metalloproteinases-2 (MMP-2), MMP-9 and vascular endothelial growth factor (VEGF) expression." (PMID 27042161, 2016). "RNA sequencing revealed a number of genes differentially expressed in lung tumors lacking Akt2 and five of these genes, Actc1, Bpifa1, Mmp2, Ntrk2, and Scgb3a2 have been implicated in human lung cancer." (PMID 26654940, 2016). "In our study, we showed that basigin-2 was highly expressed in the lung cancer bone metastases and could regulate the downstream molecules MMP-2, MMP-9 and VEGF expression, which promoted migration, invasion and proliferation of lung cancer cells." (PMID 27042161, 2016). "In humans, over expression of MMP-2, -7 and -9 in both early and late stages of lung cancer indicates that imaging these proteins may be useful in detecting and monitoring lung cancer progression." (PMID 26193700, 2015).